STAT3 (signal transducer and activator of transcription 3)
Diseases named in the same sentence as STAT3 in open-access papers (continued):
Sharing a sentence is not in itself a finding about the gene and the disease.
tumor (continued). "We observed that tumor cells adjacent to blood vessels show strong phosphorylation of STAT3, a key mediator of tumor progression." (PMID 24533454, 2014). "Autocrine/paracrine tumor suppressive signaling of the gp130/JAK/STAT3 pathway can also be activated in MTC cells in response to Ras or Raf activation." (PMID 24662939, 2014). "Small molecule inhibitors are also candidates for suppressing STAT3 activity, as they produce a similar anti-tumor inflammatory microenvironment as siRNA-mediated knockdown of STAT3." (PMID 24518612, 2014). "Beyond cellular mobility, STAT3 regulates several critical biological processes in tumorigenesis including cell-cycle progression, apoptosis, tumor angiogenesis and tumor-cell evasion of the immune system." (PMID 25216529, 2014). "STAT3 activation has been demonstrated in HNSCC tumor samples obtained from patients that developed resistance to cetuximab or cisplatin treatment." (PMID 24675768, 2014). "In the present study we demonstrate that dietary AXT inhibits tumour progression based on abrogation of the JAK/STAT3 pathway and its downstream targets cyclin D1, MMP-2, -9, and VEGF in the HBP carcinogenesis model." (PMID 25296162, 2014). "The STAT3 decoy oligonucleotide has been studied as anti-tumor agent in several types of cancer such as ovarian, breast, hepatocellular, and lung cancer as well as malignant glioma." (PMID 24404126, 2014). "STAT3 is known as an oncogene and the consistent activation of STAT3 proteins has been characterized in tumor tissues or in cell lines derived from human tumors in accumulated reports." (PMID 25126546, 2014). "Other studies have shown that Gadd45a inhibits tumor angiogenesis via blocking of the mTOR/STAT3 pathway." (PMID 24658029, 2014). "In comparison, transfection of a double STAT3 mutant in which both Y705 and S727 cannot be phosphorylated led to significant tumor growth in SCID mice." (PMID 24995504, 2014). "We acknowledge that studies need to be done to further define the role of intratumoral STAT3 activation in mediating trastuzumab resistance using clinical tumor samples." (PMID 25327561, 2014). "Activated STAT3 thus has a striking ability to promote cancer cell survival, invasion, and stemness while suppressing anti-tumor immunity." (PMID 25153725, 2014). "Despite the findings of STAT3 hyperactivation in many cancers, the role of STAT3 in oncogenesis is still unclear and is likely dependent on tumor type and cellular context." (PMID 24743777, 2014). "In the second half, we will summarize the evidence supporting that STAT3 can function as a tumor suppressor." (PMID 24995504, 2014). "Over the last decade, a large number of tumor-derived cell lines, as well as many primary human cancer tissues have been reported to overexpress and/or constitutively activate STAT3." (PMID 25268165, 2014). "In this study, we aimed to examine the effects of STAT3 decoy oligonucleotide on tumor angiogenesis." (PMID 24404126, 2014). "Two recent reports on garcinol mediated inhibition of growth of xenografted tumor developed from different cancer sources in the context of STAT3 function further underscore the therapeutic implications of garcinol." (PMID 24655440, 2014). "We observed that there was upregulation of phosphorylated STAT3 in tumor-treated CD14+/HLA-DRlow/− cells as compared to untreated CD14+ cells by Western blotting." (PMID 24652403, 2014). "In order to elucidate this, the JAK2/STAT3 signaling pathway was downregulated in the present study, as IL-6 and STAT3 work together in the tumor microenvironment to promote several cancer hallmarks, for example increased proliferation, survival and invasion." (PMID 24527098, 2014). "Constitutive STAT3 activation in tumour cells contributes to an expansion of tumour cells by promoting cell proliferation, survival, angiogenesis, and tissue remodelling." (PMID 24757565, 2014).
tumor (continued). "In other studies, it has been demonstrated that STAT3β can abolish the transcriptional activation of several STAT3 downstream targets including Cyclin D1, Bcl-xL and Mcl-1, leading to inhibition of tumor growth and promotion of apoptosis." (PMID 24995504, 2014). "STAT3 is one of the transcription factors reported to play an important role in tumor survival, proliferation, angiogenesis and metastasis." (PMID 25146150, 2014). "The first experimental evidence to support that STAT3 carries tumor suppressor functions comes from a study published in 2008." (PMID 24995504, 2014). "Moreover, it strongly contributes to the ability of primary Stat3C/C MEFs to undergo malignant transformation upon spontaneous immortalization, a feature that may explain the well known causative link between STAT3 constitutive activity and tumor transformation under chronic inflammatory conditions." (PMID 25089666, 2014). "It is well known that activated STAT3 can regulate the transcription of its target genes, which play important roles in the processes of oncogenesis including tumor angiogenesis, tumor cell invasion and metastasis." (PMID 24846175, 2014). "ROS is known to activate various transcription factors including STAT3 to regulate wide variety of cellular processes including inflammation, cell transformation, tumor cell survival, proliferation, invasion, angiogenesis, and metastasis." (PMID 24796733, 2014). "STAT3 directly and indirectly upregulates the expression of genes that are required for uncontrolled proliferation and invasion of tumor cells." (PMID 25344679, 2014). "It indicates that various signaling pathways canmodulate serine phosphorylation of Mt STAT3 in tumor cells." (PMID 25299776, 2014). "JSI-124, also known as cucurbitacin I, is a selective inhibitor of Janus kinase/signal transducer and activator of transcription 3 (JAK/STAT3), and in vitro and in vivo studies have found that it has anti-tumor and anti-proliferative properties." (PMID 25013518, 2014). "COX-2-derived prostaglandins, particularly PGE2, upregulate VEGF and STAT-3 production, ultimately promoting tumor angiogenesis." (PMID 25505736, 2014). "Combined trastuzumab with STAT3 inhibition synergistically suppressed the growth of the trastuzumab-resistant tumor xenografts in vivo." (PMID 25327561, 2014). "It is possible that STAT3 signaling is developmental biologically programmed to be tumor suppressive in thyroid epithelium." (PMID 24662939, 2014). "The inhibition or genetic ablation of STAT3 relieves immunosuppression and thus markedly ameliorates anti-tumor responses." (PMID 24473086, 2014). "For example, small molecule inhibitors of JAK, Src, Bcr-Abl, and EGFR have all been shown to block STAT3 signaling and induce tumor cell apoptosis." (PMID 24675568, 2014). "AZD1480 is a potent, competitive small-molecule inhibitor of JAK1/2 kinase which inhibits STAT3 phosphorylation and tumor growth." (PMID 25149535, 2014). "While STAT3 can directly regulate several genes that support tumor growth, these effects are compounded by the upregulation of c-Fos and HIF-1α expression." (PMID 24743777, 2014). "Inhibition of Stat3 can result in the suppression of tumor angiogenesis, which was also observed in tumor tissues treated with niclosamide in this study." (PMID 24416452, 2014). "These phenotypes relied on STAT3 signaling since cells inhibited or silenced for STAT3 lost their stem-like features and high tumorigenicity in tumor-take rate experiments." (PMID 25026286, 2014). "It has been reported that the activation of STAT3 in tumor cells promotes tumor growth by increasing the capacity of tumors to evade the immune system." (PMID 24789104, 2014). "Growing evidence suggests that Stat3 functions as an oncogene and plays a critical role in transformation and tumour progression." (PMID 25297811, 2014).
tumor (continued). "A number of STAT3 inhibitors have been evaluated for their antitumor activity in vitro and in vivo in experimental tumor models and several approved therapeutic agents have been reported to function as STAT3 inhibitors." (PMID 24662938, 2014). "Intra-peritoneal injection of garcinol into nude mice bearing subcutaneous PLC/PRF5 xenografts resulted in significant suppression of tumor progression and suppression of expression of p-STAT3 in garcinol treated tumor tissues." (PMID 24655440, 2014). "While the oncogenic effects of STAT3 have been well recognized, a relatively small number of studies published previously have shown that STAT3 carries tumor suppressor functions, a seemingly paradoxical notion." (PMID 24995504, 2014). "Reciprocally, secreted factors, including FGF, EGF, HGF, chemokines and cytokines, from stromal cells have paracrine effects which activate STAT3 in tumor cells." (PMID 24722453, 2014). "Phosphorylated (p-) STAT-3 induces tumor angiogenesis by upregulating the expression of VEGF and modulates immune functions facilitating immune evasion." (PMID 24883303, 2014). "They observed an inhibitor-dependent decrease of STAT3 phosphorylation, which provoked abrogated tumor growth, sphere formation ability, and increased radio- and chemo-sensitivity (cisplatin, doxorubicin, paclitaxel) in CD133+ NSCLC cells." (PMID 25268165, 2014). "STAT3 is a transcription factor that is constitutively activated in many types of cancer, contributing to tumor progression via several mechanisms." (PMID 25344679, 2014). "AZD1480 is a potent, competitive small-molecule inhibitor of JAK1/2 kinases, that is capable of blocking STAT3 phosphorylation and inhibiting tumor growth in a STAT3-dependent manner." (PMID 25149535, 2014). "It was found that STAT3 inhibition by AG490 significantly inhibited tumor growth, compared with DMSO-treated or untreated controls." (PMID 24527098, 2014). "We observed that tumor cells adjacent to blood vessels showed phosphorylation of STAT3, Akt, and ERK." (PMID 24533454, 2014). "Subsequent reduction of several regulatory substrates of STAT3, such as cyclin D and survivin, leads to inhibition of tumor growth mainly through induction of apoptosis." (PMID 24952874, 2014). "In line with reported studies the suppression of STAT3 activity in BC cells strongly impacted on primary tumor growth and STAT3-silenced cells grew significantly less than control cells." (PMID 25026286, 2014). "STAT3 activity in tumor cells has been demonstrated to facilitate the expansion and maintenance of CSCs in several tumor types." (PMID 24652403, 2014). "Through regulating gene expression, STAT3 has been demonstrated to play a pivotal role in many cellular processes including oncogenesis, tumor growth and progression, and stemness." (PMID 24743777, 2014). "While blocking STAT3 signaling can induce apoptosis and inhibit angiogenesis in tumor cells, low levels of STAT3 can still stimulate proliferation by inducing the expression of CyclinD1 and CDK4." (PMID 25007077, 2014). "STAT3 is constitutively activated in many types of human cancers and plays crucial roles in regulating tumor cell proliferation, survival, invasion, angiogenesis, and immune evasion." (PMID 25327561, 2014). "Previous studies have indicated that the IL-6/ gp130/JAK signaling pathway can phosphorylate STAT3 Tyr705 in various tumor cells, including HCC." (PMID 24655440, 2014). "STAT3 induces target gene transcription of pro-survival and proliferative genes such as Bcl2 or cyclin D1 that promote tumor growth and survival." (PMID 24473086, 2014). "Below, we discuss what is known about how OSM engages JAK/STAT3 signaling to engage tumor suppressive signaling, and paradoxically to promote tumor progression, metastasis, and cancer stem cell expansion." (PMID 24675570, 2014).
tumor (continued). "Histologic examination showed that there was much less evidence of tumor cells in the vitreous cavity between the lens and the retina in mice receiving STAT3 siRNA treatment, compared to the eyes which were full of tumors in control mice." (PMID 25359779, 2014). "It is likely that STAT3 phosphorylation reprograms monocytes to acquire a pro-tumor, immunosuppressive (MDSC) phenotype." (PMID 24652403, 2014). "STAT3 has been shown to up regulate tumor angiogenesis by directly targeting multiple pro-angiogenic factors." (PMID 24743777, 2014). "It has been shown that ablation of STAT3 expression markedly reduced the expansion of MDSCs and promoted the accumulation of DCs in tumor-bearing mice." (PMID 25149535, 2014). "In small cell lung cancer, CXCL12 can stimulate JAK2/STAT3 constitutive phosphorylation, which is important in tumor cell growth and spreading." (PMID 25405202, 2014). "Recent studies have shown that STAT3 is constitutively activated in tumor cells and is overexpressed in cisplatin-resistant cell lines." (PMID 24675768, 2014). "Constitutively Y-P STAT3 is observed in many tumors that become addicted to its activity, and STAT3 transcriptional activation is required for tumor transformation downstream of several oncogenes." (PMID 25089666, 2014). "We will discuss the regulation of STAT3 target genes that result in the tumor supporting functions of STAT3, including several transcription factors, apoptosis, tumor immune surveillance, metastasis, tumor angiogenesis, and oncogenic cell signaling." (PMID 24743777, 2014). "Differences between tumor and normal cells were detected in nuclear stainings of total STAT3, with higher expression levels in carcinoma tissues." (PMID 25268165, 2014). "STAT3 can promote tumor growth by mechanisms within the tumor cell as well as in the tumor microenvironment." (PMID 24743777, 2014). "The therapeutic effect of S3I-201 in xenografts of HCC cell line Huh7 was that it inhibited Stat3 tyrosine phosphorylation and tumor growth at a dose of 5 mg/kg given every other day." (PMID 25057499, 2014). "WP1066 and presumably other inhibitors of STAT3 activation can block these actions to inhibit gastric inflammation, cell proliferation and promote apoptosis and therefore block tumour development." (PMID 24804649, 2014). "Closer observation of tumor growth rates indicated that impairment of STAT3 signaling impacted in a dual manner in BC tumor growth." (PMID 25026286, 2014). "Tumor cells from mice which survived the paclitaxel treatment were found to have an activated JAK2/STAT3 pathway and to have significantly enhanced staining of embryonic stem cell transcription factor Oct4 and CSC-like marker CD117." (PMID 24782986, 2014). "Although aberrant STAT3 activity mediates oncogenic signaling in many different cancers, STAT3 is also known for its tumor suppressive effects." (PMID 24662939, 2014). "Activated Stat3 has been shown to protect tumour cells from apoptosis and promote cell proliferation by regulating genes coding anti-apoptotic and proliferation-associated proteins such as Bcl, Ccnd1 and c-Myc." (PMID 25297811, 2014). "STAT3 participates in tumor immune tolerance by inhibiting proinflammatory mediators and stimulating immune suppressing factors." (PMID 25594054, 2014). "Vascular Endothelial Growth Factor (VEGF) is the most important inducer of tumor mediated angiogenesis and STAT3 is a direct transcriptional activator of VEGF." (PMID 24722453, 2014). "Trying to understand the relationship between these endothelial cell-initiated signaling events on tumor cells, we exposed tumor cells to endothelial cell conditioned medium in the presence of chemical inhibitors of STAT3, Akt, and ERK pathways." (PMID 24533454, 2014).
tumor (continued). "While the mechanisms underlying these observations require further investigations, these results have suggested the relevance of ras and/or p19ARF in regulating the tumor suppressor function of STAT3." (PMID 24995504, 2014). "For example, STAT3 activation in tumor cells can induce genes involved in the impairment of dendritic cell maturation, which results in the inhibition of T cell activation." (PMID 24662939, 2014). "Previous studies have confirmed that STAT3 alterations affect Bcl-2 and Bax protein expression (decreased Bcl-2 and increased Bax) and induce inflammation and apoptosis in many types of tumor cells." (PMID 25092271, 2014). "In other words, downregulation of IL-6 secreted by endothelial cells inhibits phosphorylation of STAT3 in tumor cells, which will then secrete less angiogenic factors (e.g. CXCL8) causing a decrease in tumor microvessel density and tumor growth." (PMID 24533454, 2014). "In order to confirm our in vitro findings, we examined the in vivo ability of STAT3 decoy oligonucleotide to inhibit tumor angiogenesis." (PMID 24404126, 2014). "Blocking STAT3 in immune cells can generate diverse anti-tumor immunity by suppressing negative regulators such as immature dendritic cells and regulatory T cells and activating CD8+ T cells, natural killer cells and neutrophils." (PMID 25594054, 2014). "It is highly likely that STAT3 will give a selective advantage, and as STAT3 activation is a late event, one can conjecture that a slight loss of proliferative activity is an acceptable cost for acquisition of other features which may be more relevant to the tumour at that stage." (PMID 25348333, 2014). "STAT3 can directly regulate a host of genes that ultimately support tumor growth and progression such as genes involved in cell signaling, tumor angiogenesis, and metastasis." (PMID 24743777, 2014). "The development of agents that target STAT-3 with adequate potency and tumour selectivity has proven to be a difficult task." (PMID 25296162, 2014). "More importantly, activation of STAT3 in tumor infiltrating immune cells has been shown to be responsible, in part, for their immune-suppressed phenotype." (PMID 24806510, 2014). "Nevertheless, results from more recent experimental and clinicopathologic studies have suggested that STAT3 also can exert tumor suppressor effects under specific conditions." (PMID 24995504, 2014). "Given the delicate balance between STAT3’s tumor promoting and tumor suppressing actions it is critical to assess the net effect of STAT3 inhibition within the tumor and the impact on tumor surveillance." (PMID 24473086, 2014). "A number of STAT3 inhibitors have been identified and evaluated their antitumor activity in vitro and in vivo in experimental tumor models." (PMID 24662938, 2014). "On the other hand, NSC 74859, one of the novel STAT3 inhibitors, significantly suppresses tumor growth in vitro and in vivo." (PMID 24520293, 2014). "Several preclinical studies have demonstrated the anti-tumor effects of STAT3 knockdown using small interfering RNA (siRNA), micro-RNA (miRNA), or small molecule inhibitors." (PMID 24518612, 2014). "STAT3 has a critical role in liver inflammation and tumor progression because it can be triggered by cytokines and growth factors such EGFR, FGFR and PDGF through tyrosine phosphorylation." (PMID 24418169, 2014). "Garcinol also inhibited the growth of human HCC cells in a xenograft mouse model and modulated the activation of STAT3 in the tumor tissues." (PMID 24655440, 2014). "STAT3 regulates a number of genes that are critical to tumor cell survival and proliferation, angiogenesis, invasion, metastasis and immune evasion." (PMID 24520283, 2014). "To determine if the effects of blocking STAT3 activation on tumor cells were applicable to tumors in vivo, we first tested tumor xenografts in athymic nude mice inoculated with PC3M-1E8 cells." (PMID 25261365, 2014).